GPBAR1 (G protein-coupled bile acid receptor 1)
Diseases named in the same sentence as GPBAR1 in open-access papers (continued):
Sharing a sentence is not in itself a finding about the gene and the disease.
hyperlipidemia (6 papers, 2014 to 2025). "Activation of FXR is an effective treatment of hyperlipidemia.The FXR agonist 6-ethyl-CDCA, known as obeticholic acid (OCA), additionally activates the GPBAR1/TGR5 and is responsible for unwanted effects of synthetic FXR ligands such as itching." (PMID 36355476, 2022).
gastric adenocarcinoma (5 papers, 2016 to 2022). "A previous report stated that GPBAR1 is highly expressed in human gastric adenocarcinoma and is positively correlated with the expression of the epithelial-mesenchymal transition (EMT) marker N-cadherin." (PMID 34222478, 2021). "In the present study we provide evidence that GPBAR1 is expressed in the normal gastric mucosa and that its expression, as measured by RT-PCR, increases significantly in tumor patients with advanced gastric adenocarcinomas (stage III and IV)." (PMID 27409173, 2016). "Here, we have examined the expression of GPBAR1 in human gastric adenocarcinomas and investigated whether its activation promotes the acquisition of a pro-metastatic phenotype." (PMID 27409173, 2016). "It suggests that GPBAR1 may be involved in gastric adenocarcinoma." (PMID 34222478, 2021). "However, the expression of the receptor was not constantly upregulated in gastric adenocarcinoma cells (intestinal and diffuse type), indicating that neither the presence of metaplasia or histologic subtype of the tumor was associated with a specific pattern of GPBAR1 gene expression." (PMID 27409173, 2016).
lipid metabolism disorder (5 papers, 2023 to 2026). "G protein-coupled bile acid receptor 1 (TGR5) is a potential therapeutic target for glucose-lipid metabolic disorders due to its capacity to stimulate glucagon-like peptide-1 (GLP-1) secretion." (PMID 41752082, 2026).
polycystic liver disease (5 papers, 2019 to 2023). "Another piece of evidence of the relevance of autophagy in the biliary tree is represented by the G protein-coupled bile acid receptor 1 (GPBAR1 or TGR5), a cAMP-linked bile acid receptor involved in polycystic liver disease (PLD)." (PMID 30979078, 2019). "Structurally or functionally defective cilia result in several cholangiopathies (e.g., polycystic liver disease and biliary atresia) characterized by cholangiocyte hyperproliferation, possibly through apical GPBAR1 activation with increased intracellular cAMP." (PMID 36899928, 2023).
Stroke (5 papers, 2018 to 2025). Sudden impairment of blood flow to a part of the brain due to occlusion or rupture of an artery to the brain. "Further, Gpbar1 is expressed by microglia and GPBAR1 agonists have been shown to reduce neuroinflammation in several neurodegenerative diseases including models of multiple sclerosis, hepatic encephalopathy, and stroke." (PMID 30355312, 2018).
Cholestatic liver disease (4 papers, 2019 to 2025). "GPBAR1 can regulate intestinal metabolism and intestinal inflammation, but the mechanism between GPBAR1 and the gut microbiome in cholestatic liver disease remains to be further validated." (PMID 35095513, 2021). "This review specifically focuses on the function of GPBAR1 in cholestatic liver disease and summarizes the various pathways through which GPBAR1 acts in cholestatic models." (PMID 35095513, 2021). "In this review, we summarize our understanding of the role of GPBAR1 in the pathophysiology of cholestatic diseases and expound on the different pathways that mediate the effects of GPBAR1 on cholestatic liver disease." (PMID 35095513, 2021). "GPBAR1-mediated β-catenin signalling also activated PI3K/AKT and inhibited the TLR4/NF-κB pathway, thus attenuating the inflammatory response, which suggests a new mechanism by which GPBAR1 regulates cholestatic liver disease in a model of cholestatic liver injury induced by BDL." (PMID 35095513, 2021). "We summarized the roles and pathways of GPBAR1 in cholestatic liver disease." (PMID 35095513, 2021). "Therefore, dual targeting of the BA membrane receptor GPBAR1 and nuclear receptor FXR may be a promising strategy for cholestatic liver disease." (PMID 35095513, 2021).
chronic hepatitis B (4 papers, 2022 to 2024). "In addition, another study has demonstrated the diagnostic value of serum G-protein-coupled bile acid receptor Gpbar1 (TGR5) methylation in HCC and chronic hepatitis B patients." (PMID 37759769, 2023).
prostate carcinoma (4 papers, 2013 to 2025). A carcinoma that arises from epithelial cells of the prostate gland. "Our preliminary results show strong expression of GPBAR1 protein in LNCaP, PC-3 and DU-145 cells and we are currently investigating the role of this receptor in triggering various cell death or survival pathways in these prostate cancer cells." (PMID 27896021, 2016).
COVID-19 (3 papers, 2024 to 2025). A disease caused by infection with severe acute respiratory syndrome coronavirus 2. "Further connecting the dots between bile acid metabolism and both COVID-19 and MAFLD, we can explore the roles of Farnesoid-X-receptors (FXR) and G protein bile acid-activated receptor 1 (GPBAR-1), also known as Takeda G-protein-coupled receptor 5 (TGR5)." (PMID 38932276, 2024).
endothelial dysfunction (3 papers, 2015 to 2025). In vascular diseases, endothelial dysfunction is a systemic pathological state of the endothelium (the inner lining of blood vessels) and can be broadly defined as an imbalance between vasodilating and vasoconstricting substances produced by (or acting on) the endothelium. "In mice feed methionine, treatment with BAR501 attenuated endothelial dysfunction and caused a GPBAR1-dependent regulation of CSE." (PMID 26539823, 2015). "Liver endothelial dysfunction was induced by feeding wild type and Gpbar1-/- mice with methionine for 4 weeks." (PMID 26539823, 2015).
multiple sclerosis (3 papers, 2011 to 2018). A progressive autoimmune disorder affecting the central nervous system resulting in demyelination. "Agonism of GPBAR1 also had profound effects in the experimental autoimmune encephalomyelitis (EAE) mouse model of multiple sclerosis, where monocytes play an important role." (PMID 24967665, 2014). "Importantly, we demonstrated that the selective GPBAR1 agonist reduced disease severity in EAE, the mouse model of multiple sclerosis where monocyte activity is critical." (PMID 24967665, 2014).
experimental autoimmune encephalomyelitis (2 papers, 2014 to 2021). An autoimmune demyelinating disease of the central nervous system that is produced experimentally in animals by the injection of homogenized brain or spinal cord in Freund's adjuvant. "The supplementation of tauroursodeoxycholic acid (TUDCA) has been demonstrated to reduce the severity of disease through G protein-coupled bile acid receptor 1 (GPBAR1) in experimental autoimmune encephalomyelitis (EAE)." (PMID 34940570, 2021).
Acute hepatitis (1 paper, 2023). Acute hepatic injury resulting from inflammation typically accompanied by increased serum alanine transaminase activity. "Genetic depletion of GPBAR1 exacerbated liver damage in a mouse model of acute hepatitis and led to the recruitment of NKT1, a subtype of proinflammatory NKT cells." (PMID 38067153, 2023). "On the other hand, overexpression of GPBAR1 rescues wild-type mice from acute hepatitis and induces the polarization of NKT cells to an anti-inflammatory phenotype (NKT10 subtype)." (PMID 38067153, 2023).
acute pancreatitis (1 paper, 2020). An acute inflammatory process that leads to necrosis of the pancreatic parenchyma. "Qingyi Decoction ameliorated acute biliary pancreatitis by inhibiting Gpbar1/NF-κB/p-RIP, which improved intestinal myoelectrical activity and intestinal transit in odium deoxycholate (SDOC) induced acute pancreatitis rats model." (PMID 33118404, 2020).
bone metastasis (1 paper, 2022). Transfer of a neoplasm from its primary site to bones. "In addition, our results suggest that patients with high GPBAR1 are more likely to suffer bone metastasis and a poor outcome." (PMID 36755861, 2022).
fusariosis (1 paper, 2017). "Further, human orthologues of 4 genesenriched in neurons, namely tkr-3 (orthologue GPBAR1), ugt-8(orthologue UGT3A2), R05G6.5.1 (orthologue NME5), and srw-85(orthologue GPR142) might act as potential candidates to unravel the link betweenneuronal stress and fusariosis." (PMID 29152379, 2017).
ischemia reperfusion injury (1 paper, 2025). Adverse functional, metabolic, or structural changes in ischemic tissues resulting from the restoration of blood flow to the tissue (reperfusion), including swelling; hemorrhage; necrosis; and damage from free radicals. "During hepatic ischemia-reperfusion injury, GPBAR1 modulates innate immune activation, with the GPBAR1-Cat E axis influencing pro-inflammatory responses by targeting macrophage motility and polarization." (PMID 40558546, 2025).
liver cirrhosis (1 paper, 2022). "GPBAR1 was significantly upregulated in HCC than in liver cirrhosis, with normal liver having the lowest level." (PMID 36755861, 2022). "GPBAR1 expression in HCC was significantly higher than that in liver cirrhosis, followed by normal liver tissues." (PMID 36755861, 2022). "Expression of GPBAR1 in normal liver tissues, liver cirrhosis and HCC was detected with IHC and qPCR, showing that GPBAR1 expression was increased in liver cirrhosis and HCC." (PMID 36755861, 2022).
ovarian dysfunction (1 paper, 2024). The inability of the ovaries to function. "This reduction in GPBAR1 expression appears to be closely linked to ovarian dysfunction and hormone imbalance observed in PCOS patients." (PMID 39850756, 2024).
rosacea (1 paper, 2023). A chronic erythematous skin disorder that affects the face. "Another study showed that rosacea patients have distinct levels of bile acids, including elevated lithocholic acid, which can stimulate the production of inflammatory cytokines and chemokines via activation of the G protein-coupled bile acid receptor 1 (GPBAR1)." (PMID 37626650, 2023).
serous ovarian cancer (1 paper, 2024). "A recent study has reported that G-protein-coupled bile acid receptor-1 (GPBAR1) is overexpressed in patients with serous ovarian cancer (SOC) and is significantly associated with the poor prognosis of OC." (PMID 39678497, 2024).
metabolic disorders (85 papers, 2015 to 2026). "Oleanolic acid is one of the rare natural ligands of GPBAR1, showing robust antidiabetic effects on high-fat-fed mice, matching the potential effect of GPBAR1 to improve metabolic disorders." (PMID 35095513, 2021). "The role of GPBAR1 in metabolic diseases has always been a hot topic of research." (PMID 35095513, 2021). "GPBAR1 activation affects energy expenditure, glucose metabolism, and insulin sensitivity; thus, the exogenous modulation of the receptor representing an attractive strategy to treat metabolic disorders." (PMID 30884797, 2019). "The high GPBAR1 activity efficacy and the optimal pharmacokinetic profile of the new compounds place the ((1,2,4-oxadiazol-5-yl)pyrrolidin-3-yl)ureidyl scaffold in an optimal fashion for further investigations to achieve drug candidates to treat GPBAR1-related metabolic disorders." (PMID 30792450, 2019). "Among these receptors, the farnesoid X receptor (FXR) and the membrane G-coupled receptor (GPBAR1) have gained increasing consideration as druggable receptors and their exogenous dual regulation represents an attractive strategy in the treatment of enterohepatic and metabolic disorders." (PMID 27381677, 2016). "Inflammatory, systemic metabolic disorders in the liver and brain are regulated by the bile acid-activated receptors FXR and GPBAR1, which are potential therapeutic targets." (PMID 36361829, 2022). "With the increasing frequency of metabolic disorders in the western population, dual FXR antagonistic/GPBAR1 agonistic potency represents an interesting synergistic pharmacological intervention and therapeutic application to this issue." (PMID 34483922, 2021).
cancer (44 papers, 2014 to 2026). A tumor composed of atypical neoplastic, often pleomorphic cells that invade other tissues. "Among these receptors, the transmembrane G protein-coupled bile acid receptor 1 (GPBAR1, also called TGR5), is of particular interest in the context of cancer cachexia for two main reasons." (PMID 34945009, 2021). "Expression of GPBAR1, mRNA and protein, was detected in cancer cell lines, with MKN 45 having the higher expression." (PMID 27409173, 2016). "LCA anticancer properties in relation to BC in general, include reductions in cancer cell proliferation and epithelial to mesenchymal cell transition inhibition acting via the G-protein-coupled bile acid receptor 1 (TGR5) that exerts downstream anti-inflammatory effects." (PMID 36505861, 2022). "Emerging evidence has shown the involvement of GPBAR1 in cancer progression." (PMID 36755861, 2022). "The functions of GPBAR1 in cancer are still very controversial." (PMID 36755861, 2022). "The expression and molecular function of GPBAR1 in different cancer types may be context- and tissue-dependent." (PMID 36755861, 2022). "Therefore, in the context of CCA, inhibiting GPBAR1 expression at least partially inhibits the proliferation and migration of cancer cells, indicating that GPBAR1 may be a potential therapeutic target for CCA treatment." (PMID 35095513, 2021). "GPBAR-1 activation, i.e., by DCA treatment, transactivates EGFR–STAT3 signalling, which plays an important role in cancer progression." (PMID 33266235, 2020). "These alterations, in turn, can engage host BA receptors like Farnesoid X Receptor (FXR) and Takeda G protein-coupled Receptor 5 (TGR5/GPBAR1) on immune and cancer cells, thereby influencing anti-tumor immune responses and the efficacy of treatments such as immune checkpoint inhibitors (ICIs)." (PMID 40821794, 2025). "The effects that various bile acid species exert on cancer growth and progression are dependent on their concentrations and cellular environment as well as differential expression of their main receptors, the Farnesoid-X-Receptor (FXR) and the bile acid activated G protein coupled receptor (GPBAR1)." (PMID 36998446, 2023). "Instead, GPBAR1 was not detectable in both cancer and adjacent normal tissues." (PMID 36998446, 2023). "In contrast, the synthetic agonism of another common bile acid receptor, the G protein-coupled bile acid receptor TGR5 (GPBAR1) which is mainly activated by secondary bile acids, failed to significantly alter cancer cell dynamics." (PMID 38611046, 2024).
tumor (40 papers, 2016 to 2026). "Members of the IL1 family, including IL1B, IL33, and IL18, are upregulated in the GPBAR1 tumors and are generally identified as contributors to tumor immunosuppression." (PMID 36834607, 2023). "This conclusion indicates that patients with high GPBAR1 expression should get more severe surveillance for tumor recurrence and more intensive precision treatment." (PMID 36755861, 2022). "In HCC tissues, GPBAR1 expression was significantly higher than that in tumor-adjacent tissues, indicating a potential oncogenic role for GPBAR1 in HCC." (PMID 36755861, 2022). "Furthermore, TGR5 (also known as GPBAR1) was found on infiltrated TAMs, where it affects anti-tumor immunity by contributing to TAM-mediated blockage of CD8+ T cell functions and overall survival in NSCLC patients." (PMID 41023740, 2025). "GPBAR1 was more highly expressed in HCC tissues than in tumor-adjacent tissues." (PMID 36755861, 2022). "In addition to GPBAR1, multiple tumor numbers, positive vascular invasion, advanced T stage, and TNM stage were all significantly associated with a poor prognosis for HCC." (PMID 36755861, 2022). "Because targeting EMT is a promising approach to protect from metastasis formation, we have further investigated whether activation of GPBAR1 induces changes in the expression of a subset of genes known to be involved in tumor diffusion." (PMID 27409173, 2016). "Nanodelivery of BA receptor modulators—such as the FXR agonist obeticholic acid (OCA) and the GPBAR1 antagonist 5β-cholanic acid (5β-CA)—enhanced NK, NKT, and CD8+ T cell infiltration and triggered potent anti-tumor responses in liver cancer models." (PMID 40821794, 2025). "In our study, we investigated the expression of G-protein-coupled bile acid receptor (GPBAR1) in HCC tissues and tumor-adjacent tissues by qRT-PCR and immunohistochemistry." (PMID 36755861, 2022). "In our study, we investigated the expression of GPBAR1 in HCC tissues and tumor-adjacent tissues." (PMID 36755861, 2022). "The expressions of GPBAR1 in HCC and tumor-adjacent tissues were first assessed by mRNA." (PMID 36755861, 2022).
liver (6 papers, 2015 to 2025). "GPBAR1 (TGR5) appears to have cell-specific effects that can either promote or antagonize components of cholestatic liver injury." (PMID 36899928, 2023). "The livers of GPBAR1-KO mice accumulated excessive hydrophobic BA pools and exhibited excessive liver inflammation, suggesting that GPBAR1 could control bile hydrophobicity, as well as cytokine secretion under BA overload after PH." (PMID 35095513, 2021). "CYSLTR1 is expressed in LSECs and monocytes, and its inhibition in conjunction with a G protein-coupled bile acid receptor 1 (GPBAR1) agonist potently reverses LSEC/monocyte interactions and reduces liver damage." (PMID 40595432, 2025).
adenocarcinoma (2 papers, 2016 to 2022). A common cancer characterized by the presence of malignant glandular cells. "GPBAR1 (also known as TGR5) is a bile acid activated receptor expressed in several adenocarcinomas and its activation by secondary bile acids increases intestinal cell proliferation." (PMID 27409173, 2016).
immune dysfunction (2 papers, 2018 to 2022). "In this model, obeticholic acid and INT-767, two dual GPBAR1 and FXR agonists, as well as the selective GPBAR1 agonist, INT-767, attenuate immune dysfunction-induced fibrosis by multiple mechanisms." (PMID 30150987, 2018).
brain diseases (1 paper, 2022). "We also recommend the development of dual GPBAR1/FXR ligands to reduce side effects and manage NAFLD and brain disease efficiently." (PMID 36361829, 2022).
GPBAR1 also shares sentences with these, for which no sentence is quoted: metabolic syndrome (23 papers); Hyperglycemia (16); non-alcoholic fatty liver disease (11); colon cancer (10); gallstones (9); infection (9); inflammation (9); kidney disease (9); cardiac hypertrophy (7); Glucose intolerance (7); diabetic cardiomyopathy (6); sarcopenia (6); Alzheimer disease (5); Cirrhosis (5); esophageal adenocarcinoma (5); heart failure (5); mastitis (5); neurological diseases (5); osteoporosis (5); portal hypertension (5); viral infection (5); diabetic nephropathy (4); diabetic retinopathy (4); endotoxemia (4); irritable bowel syndrome (4); lung carcinoma (4); neurodegenerative disease (4); renal fibrosis (4); ulcerative colitis (4); esophageal cancer (3).
A further 133 diseases each share a sentence with GPBAR1 in 3 papers or fewer.